HEY1 (hes related family bHLH transcription factor with YRPW motif 1)
Diseases named in the same sentence as HEY1 in open-access papers (continued):
Sharing a sentence is not in itself a finding about the gene and the disease.
tumor (continued). "We confirmed that knockdown of PINK1 increased tumor sphere formation, suggesting that HEY1 may confer cancer cell stemness properties through PINK1." (PMID 31819034, 2019). "For instance, a higher expression of ASCL1, Dll1, Notch1, -3, -4, and Hey1 correlates with a higher glioma grade and a worse prognosis, indicating that more activated Notch signaling promotes a more undifferentiated and aggressive tumor phenotype." (PMID 30832246, 2019). "HEY1 was also highly expressed in HCC tumor cells according to Wang’s cohort (GSE14520)." (PMID 29212240, 2017). "HEY1 has been found to be expressed within solid CNS tumors, and the blockade of HEY1 via antisense oligonucleotide has been shown to inhibit hallmarks of the tumor phenotype in vitro." (PMID 28574840, 2017). "Altogether, LDB2 inhibits tumor cell proliferation and migration by targeting HEY1." (PMID 29212240, 2017). "Additionally, analysis of the expression of the target genes Hes1, Hey1 and Hey2 suggested variable activation which differed substantially between clonal cell lines, tumor xenografts and normal pituitaries." (PMID 28915655, 2017). "The hypoxia-Notch gene subset (HIF-1α/PGK1/VEGF/CA9/OPN-Notch1/Dll1/Hes1/Hes6/Hey1/Hey2) identified by us might hold prognostic implication and offer new opportunities in tumor sub-classification and targeted therapy." (PMID 25734817, 2015). "Therefore, we suggest that endothelial Jagged1 is able to regulate tumor cell metabolism by its angiocrine function through Notch3/Hey1." (PMID 26213336, 2015). "Given the significant activation of Notch signaling, by Hey1 transcription and expression, observed in tumor cells adjacent to the vasculature, we hypothesized that a specific Notch receptor was being activated by endothelial Jagged1." (PMID 26213336, 2015). "Interestingly, we observed increased and decreased Hey1 staining in tumor cells adjacent to the vessels, in OE and KO samples, respectively, relative to controls." (PMID 26213336, 2015). "In addition, depletion of NRARP and HEY1 impairs the stemness maintenance of liver CSCs and tumour propagation." (PMID 25985737, 2015). "Additionally, endothelial Jagged1 appears to exert an angiocrine function possibly by activating Notch3/Hey1 in tumor cells, promoting proliferation, survival and epithelial-to-mesenchymal transition (EMT), potentiating tumor development." (PMID 26213336, 2015). "The dynamic nature of CSCs or persistent NOTCH2 activation may contribute to the high number of C8orf4−/N2ICDnuc/HEY1+ cells in advanced HCC tumours and correlation in the patient cohort." (PMID 25985737, 2015). "Expression of HEY1 transcript was assessed in 15 CYLD defective tumours." (PMID 25565632, 2014). "Additional evidences are also suggestive of a tumor suppressor function of Notch in PC, including the observations of downregulation of HEY1 and of activated Notch1, and prevention of luminal cell differentiation and induction of proliferation in Notch1 knock-out models." (PMID 24684754, 2014). "Similarly, HEY1 expression was elevated in each tumor group by a fold-change ranging from 6 to 10.2 (p ≤ 0.001)." (PMID 23816051, 2013). "The first one, represented by female V006 showed moderate but widespread Hes1 expression, moderate estrogen receptor staining, undetectable p63 expression, normal E-cadherin distribution, and a marked up-regulation of Ki67 and Hey1 expression in the tumor area." (PMID 23826634, 2013). "In tumors in which Notch signaling plays a tumor-suppressive role, such as ES, agents that can selectively activate Notch receptors or induce downstream molecules such as HEY1 may be promising therapeutic approaches." (PMID 23158439, 2012). "Since SM22α is co-ordinately regulated by Notch and TGF-β, we hypothesized that the cytoplasmic domain of CD248 would similarly regulate expression of Hes and Hey1, downstream effectors of Notch that also exhibit context-specific tumor suppressor properties." (PMID 21549007, 2011).
tumor (continued). "This is accompanied by transcription of several genes, including Hes, Hey1 and SM22α, all of which may exhibit tumor suppressor properties." (PMID 21549007, 2011). "The AKR1C3+ cells could catalyze the paclitaxel to the non-toxic hydroxyl metabolites, accompanied with activated ROS and inflammation; the IDO1+ cells may inhibit T cell function by consuming tyrosine and HEY1+ cells enhanced the cell proliferation to promote tumor survival." (PMID 38227591, 2024). "Interestingly, metastatic cells cultured on Jag1 expressed higher levels of Hes1, a target gene that has high expression in cells derived from the primary tumors, while exposure to Jag2 increased expression of Hey1 in both primary tumor and metastasis-derived cells." (PMID 37202533, 2023). "The GSEA revealed that the genes correlated with PLCB1, including HEY1, EZH2, VEGFA, E2F3, and STC1, were enriched in angiogenesis, suggesting that the increased expression of PLCB1 might be associated with HCC recurrence via tumor-associated angiogenesis." (PMID 35707353, 2022). "Moreover, HEY1 deletion also impaired migration ability of tumor cells." (PMID 29212240, 2017). "Therefore, it may be potentially relevant to screen for alterations in the normal HEY1 phosphorylation levels at Ser-68 in human tumour samples." (PMID 27129302, 2016). "In addition, Hey-1 is highly expressed in KSHV tumor lesions compared to normal tissues." (PMID 27447661, 2016). "However, overall, it is apparent that hypoxic gliomaspheres mimic the in-vivo tumor condition better than the other tissue culture model as the upregulation of Notch genes (Notch1, Notch2, Notch3, Dll1, Hes1, Hey1 and Hey2) is further enhanced upon exposure to hypoxia." (PMID 25734817, 2015). "We have observed that endothelial Jagged1 contributes to tumor dysplasia through two distinct effects: a pro-angiogenic effect, increasing tumor vascular density, maturation and perfusion; and an angiocrine effect likely through Notch3/Hey1 stimulation of tumor cell proliferation." (PMID 26213336, 2015). "Nuclear HEY-1 in PDAC was strongly associated with the presence of local lymph node metastases and microvessel invasion (p = 0.003), as well as perineural invasion (p = 0.048), younger age (p = 0.022), and a trend towards association with tumour stage (p = 0.058)." (PMID 23226563, 2012). "HEY1 is a canonical Notch target, and Notch–HIF1A crosstalk is well documented in hypoxic tumor microenvironments." (PMID 41238550, 2025). "N1IC tumor cells retained the N1IC transgene and showed increased expression of Notch downstream targets Hey1 and Hes5." (PMID 39192032, 2024). "Immunostaining and flow cytometry revealed that the nuclear Notch1 ICD and Hey1 levels, respectively, were enhanced in the GIT1 knockdown tumours compared to the control tumours." (PMID 35318302, 2022). "Previous studies have shown that Hey1 can promote the EMT process and the expression of matrix metalloproteinases expression profile of tumor cells 14-16." (PMID 34729100, 2021). "After inhibiting the expression of HEY1 in SACC, we found that the volume and number of tumor cell spheroids were significantly reduced." (PMID 32025208, 2020). "Further, ST3Gal IV overexpression increased the Jagged1, Notch1, Hes1, Hey1 and p21 expression, meanwhile, decreased the expression levels of CyclinD1, CyclinE1, CDK2 and CDK4 in xenograft tumor tissues." (PMID 33598419, 2020). "The transcription factor Twist1, which is known to promote tumor metastasis and induce the EMT, was obviously reduced when HEY1 was knocked down." (PMID 32025208, 2020). "We found that the expression levels of NOTCH2, HEY1, and HES6 were lower in lncAKHE-silenced HCC cell-derived tumor tissues than in control tumor tissues, whereas YEATS4 expression was not affected." (PMID 29706630, 2018).
tumor (continued). "JAG1, JAG2, HEY1 and HES1 had relatively higher expression in tumor samples compared to the pool of normal controls." (PMID 28146432, 2017). "Consistently, high expression levels of HEY1, HES6 and NRARP in HCC tumours were validated by Zhang's cohort (GSE25097)." (PMID 25985737, 2015). "A number of Notch target genes were consistently overexpressed in CYLD defective tumours, including LEF1, HEY1 and NOTCH1." (PMID 25565632, 2014). "In summary, DLL4/Notch/Hey1/MMP9 cascade mediates a direct interplay between endothelial cells and tumor cells, which eventually promotes RCC hematogenous metastasis." (PMID 24931473, 2014). "Knockdown of PTOV1 in PC-3 cells led to a strong upregulation of HES1 and HEY1 both in vitro and in cells implanted in SCID-beige mice, accompanied with a significant delay in tumor growth and metastatic spread." (PMID 24684754, 2014). "Tumor tissues were analyzed at single-cell level by immunohistochemistry for the expression of PTOV1, HEY1 and HES1 proteins on serial sections from 20 primary tumors (n = 10 with Gleason < 7 and n = 10 with Gleason > 7) and 16 lymph node metastases." (PMID 24684754, 2014). "RT-qPCR analysis for NOTCH1, NOTCH2, HEY1 and HES1 was conducted on the normal bone/matched OSA and DFI tumor sample sets." (PMID 23816051, 2013). "Using tumor samples collected from the Lgr5-specific Ythdf1cki mouse model, qPCR analysis revealed that YTHDF1 knock-in increased the expression of NOTCH1 downstream targets, including MAML1, MAML2, HES1, and HEY1." (PMID 41423446, 2025). "Tspan5 correlation analyses of TCGA tumour samples revealed that Tspan5 expression is positively correlated with the expression of ADAM10, Notch1, Notch2, Notch3, Notch4, Hey1, vimentin, N‐cadherin and Snail, whereas it is negatively correlated with E‐cadherin in HCC tissues." (PMID 33955149, 2021). "The BCPRS-related genes (YY1, POU5F1, NKX2-3, NR2F1, HEY1, and IFNA13) showed high heterogeneity in different cells; thus, the genes can independently predict cellular composition to reflect the microenvironment of tumor tissues." (PMID 34457116, 2021). "The weight of the tumor did not vary significantly in Hey1 knock-out clones upon NT-3 invalidation by siRNA, suggesting that Hey1 is necessary for TrkC to limit tumor progression in absence of NT-3." (PMID 29750782, 2018). "Surprisingly, significant positive correlations between the expressions of POFUT1 and HES1 or HEY1 are found for healthy tissues and not for tumor ones." (PMID 30380753, 2018). "Furthermore, we checked the protein levels of NOTCH2, YEATS4, HEY1, and HES6 in tumor tissues of the xenograft experiment." (PMID 29706630, 2018). "In addition to alteration in cell proliferation, our GSEA analysis demonstrated that inhibition of KDM2A attenuates tumor angiogenesis and mRNA expression of several genes in the NOTCH signaling pathway including JAG1, NOTCH1, HEY1." (PMID 27029061, 2016). "Similarly, HEY1 silencing remarkably reduced sphere formation derived from Huh7 and HCC primary cells, as well as declined xenograft tumour growth and tumour-initiating capacity." (PMID 25985737, 2015). "We observed that HEY1, HES6 and NRARP were highly expressed in the tumour tissues of HCC patients." (PMID 25985737, 2015). "Moreover, the expression levels of NRARP, HEY1 and HES6 in tumours are positively correlated with clinical severity and prognosis of HCC patients." (PMID 25985737, 2015). "Knockdown of Hey1 decreased expression of MMP9 and attenuated tumor invasion." (PMID 24931473, 2014). "Indeed, Hes and Hey1 transcript levels in CD248CyD/CyD fibroblasts were significantly higher than in CD248WT/WT fibroblasts, in line with the role of CD248 in promoting tumor growth." (PMID 21549007, 2011). "Although genetic changes may affect the level of mRNA expression, the findings of this study showed no significant variation in tumor copy number and nucleotide mutations of the six IMAAG genes (HEY1, IFNA13, NKX2-3, NR2F1, POU5F1, and YY1)." (PMID 34457116, 2021).
tumor (continued). "The tumor inhibition rate was evaluated, followed by the quantification of messenger ribonucleic acid (mRNA) and protein expression of notch signaling components NOTCH-1, NOTCH-3, NOTCH-4, JAG-1, DLL-4, Hes-1, and Hey-1 using quantitative polymerase chain reaction (qPCR)." (PMID 26762567, 2016). "Taking into consideration that CD44 is a transcriptional target of Notch-1, apparently downstream of Hes1/Hey1, we concluded that β-elemene could attenuate tumor angiogenesis by targeting GCSCs at least in part through Notch-1 expression." (PMID 23710217, 2013). "Having previously reported that Notch3 activation appeared to be associated with more aggressive disease, we have now examined components of this pathway (Notch1, Notch3, Notch4, HES-1, HEY-1) in more detail in resectable (n = 42) and non-resectable (n = 50) tumours compared to uninvolved pancreas." (PMID 23226563, 2012). "However, alternative HEY1::NCOA2 fusions have not been reported in this tumor." (PMID 39165647, 2024). "Thus, even HES1 and HEY1 do not always track together and need to be studied independently, and their expression and function may differ depending upon cell line and tumor microenvironment." (PMID 36037042, 2022). "NOTCH2 and HEY1 mRNA expression was also elevated in tumors relative to normal bone, but was not differentially expressed between the DFI tumor groups." (PMID 23816051, 2013). "This implies that HEY1 and NR2F1 may be correlated with a malignant tumor progression phenotype rather than a tumorigenesis phenotype." (PMID 34457116, 2021). "Reverse transcriptase - quantitative PCR (RT-qPCR) was utilized to quantify HES1, HEY1, NOTCH1 and NOTCH2 gene expression in matched tumor and normal metaphyseal bone samples taken from dogs treated for appendicular OSA at the Colorado State University Veterinary Teaching Hospital." (PMID 23816051, 2013).
cancer (54 papers, 2010 to 2026). A tumor composed of atypical neoplastic, often pleomorphic cells that invade other tissues. "WFA has been reported to inhibit Notch1 and downstream signaling genes (Hes1 and Hey1) that have been implicated in cancer initiation and progression." (PMID 25264898, 2014). "In addition to its roles during embryogenesis, HEY1 has also been linked to several cancer-related pathways." (PMID 27129302, 2016). "If an association between HEY1 phosphorylation status and the cancer phenotype can be found, STK38, STK38L and other serine/threonine kinases responsible for the phosphorylation of HEY1 at Ser-68 may represent novel attractive targets for therapeutic intervention." (PMID 27129302, 2016). "The transcription factor HEY1 is recognized as a key player in the EMT‐mediated decline in survival rates among cancer patients, with its expression indicating the activation of the Notch signaling pathway." (PMID 38351531, 2024). "The treatment with CB dramatically decreases the activity of the Notch promoter at its IC50 by reducing the expression of the Notch-targeted genes Hes1 and Hey1 in both cancer cells." (PMID 38563878, 2024). "NICD levels and Notch target genes, including Hey1, Hes1, and cyclin D1 (Ccnd1), were significantly upregulated in HG-treated Met1 cancer cells, suggesting that HG activates Notch signaling." (PMID 36707514, 2023). "Se-Y is an antioxidant with cancer prevention effects, and BMP2, FGF9, and HEY1 are a class of genes associated with the cancer pathway." (PMID 37570275, 2023). "There are several other cancer-related genes on 8q, including HEY1 and RAD21, which are all candidates that we are currently evaluating." (PMID 33591953, 2021). "HEY1, an upregulated gene, has been reported to be mediator of notch signaling, showing pro-oncogenic function and promotes cancer progression." (PMID 27766950, 2016). "Expression of HES1 and HEY1 was rather enhanced in cancer tissues, reaching significance for HES1, whereas HES5 was unchanged." (PMID 25167871, 2014). "Furthermore, we uncover a previously unrecognized IKKβ-USP28-HEY1 signaling axis that governs HEY1 stability and cancer stemness, offering new opportunities for synergistic therapeutic strategies in HCC." (PMID 42189121, 2026). "In luminal A cancer, low expression of CTBP1, HEY1, HEY2 was associated with worse OS." (PMID 41463075, 2025). "To delve deeper into the MFAP5-regulated signaling pathway, we conducted a literature review and found that MFAP5 might activate the Notch2 and or HEY1 in other cancer type and Notch2 has been recognized as an oncogene that enhances invasion in GC." (PMID 39524442, 2024). "Further study showed that LDB2 could recruit the tumor suppressor protein BRD7 into the promoter of the tumor-promoting protein HEY1 and exert the anti-cancer effect." (PMID 36473369, 2023). "GADPH and HEY1 had the worst Rt values in all target genes and cancer types examined." (PMID 34422018, 2021). "Hes1 and Hey1, known as direct downstream targets of Notch, belong to an extensive family of basic helix-loop-helix (bHLH) proteins and play a critical role in the regulation of cell cycle and apoptosis in various cancers." (PMID 30606241, 2019). "Importantly, the DLL4/Notch/Hey1/MMP9 cascades connecting the endothelium to the cancer cells in metastasis were identified." (PMID 24931473, 2014). "Among those, we identified the known BMP-2 target genes Id1, Id3, Dlx2 and Hey1, and genes that could be functionally annotated to Wnt signaling, pathways in cancer or cytokine-cytokine receptor interaction and that have critical roles in osteogenesis." (PMID 21998639, 2011). "Interestingly, our panel included genes already described to be cancer predisposition genes (FAS, ITK, KIF1B, PGR and MET) or previously reported as playing important roles in cancer (ABI1, ARID5B, DNMT3A, HEY1, KDM5C, NCOA1, NUP98, and SLC34A2), or in DNA repair process (FANCF)." (PMID 30925779, 2019).